EEF1A1 (eukaryotic translation elongation factor 1 alpha 1)
Description:
Translation elongation factor that catalyzes the GTP-dependent binding of aminoacyl-tRNA (aa-tRNA) to the A-site of ribosomes during the elongation phase of protein synthesis. Base pairing between the mRNA codon and the aa-tRNA anticodon promotes GTP hydrolysis, releasing the aa-tRNA from EEF1A1 and allowing its accommodation into the ribosome. The growing protein chain is subsequently transferred from the P-site peptidyl tRNA to the A-site aa-tRNA, extending it by one amino acid through ribosome-catalyzed peptide bond formation. Also plays a role in the positive regulation of IFNG transcription in T-helper 1 cells as part of an IFNG promoter-binding complex with TXK and PARP1. Also plays a role in cytoskeleton organization by promoting actin bundling (By similarity). (Microbial infection) Required for the translation of viral proteins and viral replication during human coronavirus SARS-CoV-2 infection.
Synonyms: EF-Tu; eEF1A-1; EEF1A; EF1A; LENG7; EE1A1; EF1A1; EF1alpha1; CCS-3; CCS3; EEF-1; GRAF-1EF; PTI1
Tractability: Small molecule: a structure with a bound ligand is known. Antibody: UniProt places it where antibodies can reach, with high confidence; its Gene Ontology location is reachable by antibodies, with high confidence. PROTAC: UniProt records ubiquitination sites on it; ubiquitination databases record sites on it; its protein half-life has been measured; a small molecule that binds it is known.
Gene: Protein-coding gene on chromosome 6 (73,489,308 to 73,525,587, reverse strand). Ensembl gene ENSG00000156508.
Subcellular location: Cytoplasm; Nucleus; Nucleus, nucleolus; Cell membrane
Subcellular location (Human Protein Atlas): Cytosol
Pathways (Reactome):
Metabolism of proteins: Eukaryotic Translation Elongation; Peptide chain elongation; Protein methylation
Autophagy: Chaperone Mediated Autophagy
Cellular responses to stimuli: HSF1 activation
Disease: SARS-CoV-1 modulates host translation machinery
Immune System: Neutrophil degranulation
Gene Ontology:
Molecular function: GTPase activity; kinase activator activity; kinase binding; molecular adaptor activity; protein binding; protein kinase binding; RNA binding; translation elongation factor activity; tRNA binding; GTP binding; calmodulin binding
Biological process: cellular response to epidermal growth factor stimulus; host-mediated activation of viral genome replication; translational elongation; regulation of chaperone-mediated autophagy; translation
Cellular component: cortical actin cytoskeleton; cytoplasm; cytosol; cytosolic ribosome; extracellular exosome; extracellular region; membrane; nucleolus; nucleus; plasma membrane; ribosome; ruffle membrane; cytoplasmic side of lysosomal membrane; eukaryotic translation elongation factor 1 complex; ficolin-1-rich granule lumen; secretory granule lumen
Genetic constraint (gnomAD): Loss-of-function variants: 1 observed, 37.61 expected, observed/expected ratio (o/e) 0.0266, 90% interval 0.008 to 0.13. The synonymous counts are far from expectation, so gnomAD's model fits this gene poorly and the ratio says little. Missense variants: 177 observed, 542.08 expected, observed/expected ratio (o/e) 0.33, 90% interval 0.29 to 0.37. Synonymous variants: 219 observed, 177 expected, observed/expected ratio (o/e) 1.24, 90% interval 1.11 to 1.38.
Homologues: Orthologues: chimpanzee EEF1A1 (100% identical), dog EEF1A1 (100% identical), guinea pig EEF1A1 (100% identical), macaque EEF1A1 (100% identical), tropical clawed frog eef1a1 (97% identical), zebrafish eef1a1a (95% identical), zebrafish eef1a1b (94% identical), Caenorhabditis elegans tufm-2 (24% identical), Caenorhabditis elegans eif-2gamma (23% identical), Drosophila melanogaster eIF2gamma (23% identical), Drosophila melanogaster mEFTu2 (23% identical). Paralogues in human: EEF1A2 (92% identical), GSPT1 (35% identical), GSPT2 (35% identical), HBS1L (29% identical), TUFM (29% identical), EIF2S3B (26% identical), EIF2S3 (26% identical), EFL1 (25% identical), EIF5B (24% identical), GTPBP1 (24% identical), EEF2 (24% identical), GTPBP2 (24% identical), and 6 more.
Diseases named in the same sentence as EEF1A1 in open-access papers:
EEF1A1 is named in the same sentence as 159 diseases in open-access papers, as found by Europe PMC text mining. Sharing a sentence is not in itself a finding about the gene and the disease. The quoted sentences say what the papers report.
breast cancer (30 papers, 2009 to 2025). A primary or metastatic malignant neoplasm involving the breast. "EEF1A1 mRNA levels are downregulated in most breast cancers, and this low expression has been associated with poor prognosis for patients with ER-positive breast cancer." (PMID 33462336, 2021). "Here, we study EEF1A1 mRNA and eEF1α1 protein expression in breast cancer and investigate associations between misexpression and clinical parameters." (PMID 30224719, 2018). "Explaining this paradox, we find that EEF1A1 mRNA levels in breast carcinomas are low due to EEF1A1 allelic copy number loss, found in 27% of tumors, and cell cycle-specific expression, because mRNA levels are high in G1 and low in proliferating cells." (PMID 30224719, 2018). "In addition EEF1A1, which is present in both our dataset and in thebiogrid.org dataset is linked to both cilia and breast cancer biology." (PMID 32127582, 2020). "Similarly, in the METABRIC dataset, 27% of breast cancers showed EEF1A1 copy number loss and these tumors also expressed significantly lower EEF1A1 than tumors diploid for EEF1A1 (p < 0.0001)." (PMID 30224719, 2018). "Thus, G1 phase-specific EEF1A1 mRNA expression seems the major cause of underexpression in breast cancers." (PMID 30224719, 2018). "Next, we assessed whether mutations in EEF1A1 could account for the reduced EEF1A1 mRNA expression in breast cancers." (PMID 30224719, 2018). "As this could potentially explain why EEF1A1 mRNA levels are reduced in breast carcinoma, we thus asked whether EEF1A1 mRNA expression is cell cycle-associated." (PMID 30224719, 2018). "In breast cancer, eEF1A1 is one of the six signature genes that predict lymph node metastasis, and high expression of eEF1A1 protects tumor cells from stress-induced cell death." (PMID 39962586, 2025). "EEF1A1 is not only a translation factor but is also a pleiotropic protein found in human cancers such as breast cancer, ovarian cancer, and lung cancer." (PMID 39160465, 2024). "Eukaryotic translation elongation factor 1 alpha 1 (EEF1A1), a member of the EEF1A family, has been implicated in promoting the progression of various cancers, including lung cancer, colorectal cancer, breast cancer, gastric cancer, ovarian cancer, etc.." (PMID 38965582, 2024). "Recently, a highly conserved lncRNA called MALAT1 was found to promote pro-metastatic potential in breast cancer cells by upregulating EEF1A1 expression via epigenetic modulation of the promoter." (PMID 35456960, 2022). "eEF1A1 was reported to be increased in the periphery of mammary cancer compared with the central region, and the levels of eEF1A1 in neoplastic are relatively higher than in normal tissue." (PMID 35127825, 2021). "The eukaryotic translation elongation factor EEF1A1, which is overexpressed in the majority of breast cancers and protects tumor cells from proteotoxic stress, was the sole factor that was selected in all of the 97 test set patients." (PMID 33706810, 2021). "Similar to breast cancer, higher EEF1A1 expression predicted better FP and OS in lung cancer as well." (PMID 29342219, 2018). "Unexpectedly, therefore, we find that EEF1A1 mRNA levels are reduced in virtually all breast cancers, in particular in ductal carcinomas." (PMID 30224719, 2018). "Only 3 datasets (8%) showed overexpressed EEF1A1 mRNA levels in breast cancers (p = 2.8 × 10−5, Chi-square test)." (PMID 30224719, 2018). "This indicated that low EEF1A1 mRNA levels correlate with poor DMFS in all breast cancers (p = 3.8 × 10−5, log-rank test)." (PMID 30224719, 2018). "Using 37 analyses from 11 previously reported microarray datasets, we studied EEF1A1 mRNA expression levels in a broad range of breast cancers, including ductal, lobular, medullary and mucinous breast cancers." (PMID 30224719, 2018). "We find that at the mRNA level, EEF1A1 is underexpressed and this is an independent marker for poor patient prognosis in ER+ breast cancer." (PMID 30224719, 2018).
breast cancer (continued). "In parallel to trend seen in breast cancer, EEF1A1 mRNA levels were significantly down regulated in tumor tissue, in two studies (Hou and Garber)." (PMID 29342219, 2018). "Twenty-five out of 37 (68%) showed underexpressed EEF1A1 mRNA levels in breast cancers compared to normal breast tissue." (PMID 30224719, 2018). "Since estrogen has been shown to promote breast cancer proliferation, this suggests a direct relationship between estrogen signaling and EEF1A1 mRNA expression." (PMID 30224719, 2018). "Underexpression occurs in particular in invasive, lymph node-positive, advanced stage and postmenopausal tumors, suggesting that EEF1A1 mRNA levels typically decline as breast cancers become more malignant." (PMID 30224719, 2018). "Eukaryotic translation elongation factors 1 alpha, eEF1A1 and eEF1A2, are not only translation factors but also pleiotropic proteins that are highly expressed in human tumors, including breast cancer, ovarian cancer, and lung cancer." (PMID 25905039, 2015). "We have been able to identify important node genes in the BANs, namely DKK1 in colon cancer cells, UGT1As in breast cancer cells and EEF1A1 in pancreatic cancer, leukemia and osteosarcoma cells." (PMID 19732436, 2009). "The marked expression of the ESR1 gene at stage I, which was comparable with that of EEF1A1 (housekeeping gene), may be due to the majority of breast cancer tissues being composed of ER‐positive cells." (PMID 34730297, 2021). "The main distinction between the MMTV-tTA and EF1-tTA-based mammary cancer models is that the Eef1a1 locus drives a constitutive expression of the tTA and oncogenic KRAS in neoplastic cells independent of their differentiation state, which allows them to assume diverse developmental fates." (PMID 34145248, 2021). "We studied four potential mechanisms that could explain reduced EEF1A1 mRNA expression in breast cancer." (PMID 30224719, 2018). "We find that EEF1A1 mRNA is underexpressed in advanced breast cancers." (PMID 30224719, 2018). "Thus, together these observations indicate that at the mRNA level, EEF1A1 is underexpressed in virtually all breast cancers, but the degree of underexpression is subtype-dependent." (PMID 30224719, 2018). "The analysis revealed that higher expression of EEF1A1 was significantly associated with relapse free survival (RFS) and distant metastasis free survival (DMFS), but not with overall survival (OS) or post progression survival (PPS), in breast cancer." (PMID 29342219, 2018). "Thus, low EEF1A1 levels predict poor breast cancer patient survival, in particular for patients with ER+ tumors." (PMID 30224719, 2018). "Since, compared to normal tissues, tumor tissues are enriched for cells in S/G2/M stage of the cell cycle, these data strongly suggest that the G1-specific peak levels of EEF1A1 mRNA predominantly account for our observation that EEF1A1 mRNA levels are reduced in breast carcinoma." (PMID 30224719, 2018). "In the BANs generated, DKK1 is a highly interconnected node in the colon cancer cell lines, UGT1A family members formed a network of genes differentially expressed in breast cancer, and EEF1A1 was commonly overexpressed in pancreatic cancer, leukemia and osteosarcoma." (PMID 19732436, 2009). "We next asked whether EEF1A1 is also underexpressed in breast carcinomas at the protein level." (PMID 30224719, 2018). "We initially tested the possibility that an AKT-dependent mechanism determines the relationship between EEF1A1 and glycolysis based on earlier work showing that EEF1A2 overexpression activates AKT in human breast cancer cells." (PMID 38272231, 2024). "For instance, lncRNA MALAT1 interacted with the promoter regulatory element of eEF1A1 and affected the status of H3K4 methylation in the gene promoter in breast cancer." (PMID 35607944, 2023). "eEF1A1 was reported to promote proliferation by interacting with phospho‐Akt and STAT1 in breast cancer and hepatocellular carcinoma, respectively." (PMID 35607944, 2023).
breast cancer (continued). "Four proteins (FANCD2, EEF1A1, YWHAE, PGLS) have PPIs with at least one protein in all signatures and one protein in the breast cancer signature (ALDOC) interacts with all other four signatures." (PMID 36329531, 2022). "For instance, MALAT1 interacts with the promoter of the eukaryotic translation elongation factor 1 alpha 1 (EEF1A1) gene and upregulates EEF1A1 expression by enhancing the trimethylation of H3K4, which promotes the proliferation and invasion of breast cancer." (PMID 32486413, 2020). "However, at the mRNA transcript level, low EEF1A1 expression was an independent poor-prognostic factor with ER/PR-positive tumors; breast cancer-specific post-transcriptional regulatory events may be responsible for this discordance between the expression of EEF1A1 mRNA and protein." (PMID 31703307, 2019). "Indeed, knockdown studies demonstrated that eEF1A1 depletion led to reduced HCC cell viability and diminished breast cancer cell invasiveness." (PMID 39962586, 2025). "Using stringent multivariate analyses, which account for various other clinical variables, we also demonstrate that low EEF1A1 mRNA is an independent prognostic marker for ER+ but not for ER− breast cancer patients." (PMID 30224719, 2018). "Strikingly, these data closely resemble our earlier observation that low EEF1A1 mRNA levels are an independent marker for poor patient survival for ER+ but not for ER− breast cancer patients." (PMID 30224719, 2018). "Consistently, our qRT-PCR analyses show lower EEF1A1 mRNA levels in the breast cancer cell line MCF7 than in non-cancerous MCF10A cells." (PMID 30224719, 2018). "Further in line with this, while ER- tumors are more proliferative than ER+ tumors, as measured by the expression levels of the S phase-specific proliferation marker PCNA, EEF1A1 mRNA-low tumors are more proliferative than EEF1A1 mRNA-high tumors in ER+ but not in ER- breast cancers." (PMID 30224719, 2018). "This low mutation rate of 0.4% could not explain the broad underexpression of EEF1A1 observed in breast cancer." (PMID 30224719, 2018).
viral infection (15 papers, 2011 to 2025). "MiR-33a-5p can inhibit viral infection by targeting eukaryotic translation elongation factor 1A1 (EEF1A1)." (PMID 38304545, 2024). "The EEF1A1 protein has been reported to play a key role in several viral infections by interacting with viral proteins." (PMID 37007947, 2023). "Translation initiation factor eIF4H, eIF4A and elongation factor eEF1A1 are essential in viral infections, which suggests that translation factors can be used as drug targets for the treatment of SARS-CoV-2 infections and have therapeutic potential." (PMID 35422818, 2022). "This protein has been shown to physically interact with proteins of several viral species, specifically hepatitis delta and avian reoviruses; in the latter, the knock-down of EEF1A1 has been shown to significantly impair the virus infection cycle." (PMID 32244779, 2020). "Similar to EEF1A1, the NDUFA10 protein network is downregulated by viral infection." (PMID 32244779, 2020). "In addition to its roles in polypeptide chain elongation, the noncanonical functions of eEF1A1 have become a focus recently, such as apoptosis, virus infection, signal transduction, and tumorigenesis." (PMID 34557098, 2021).
lung carcinoma (14 papers, 2014 to 2025). "Moreover, EEF1A1 has been associated with lung cancer development in smokers." (PMID 38672772, 2024). "LNC CRYBG3 can bind to eEF1A1, which is not only a translation factor, but also a pleiotropic protein that is highly expressed in human tumors, including breast, ovarian, and lung cancers." (PMID 33809929, 2021). "The most notable among these are breast, lymphoma and lung cancer wherein EEF1A1 mRNA levels were significantly reduced in tumor cases in a total of eight, four and four unique analyses, respectively." (PMID 29342219, 2018). "In stark contrast to the observations made in breast and lung cancers, Oncomine analysis showed that EEF1A1 transcript levels were significantly elevated in brain and CNS cancers." (PMID 29342219, 2018). "The expression of mRNAs coding for eEF1A1, eEF1Bα, eEF1Bβ and eEF1Bγ in human lung cancer was assessed by Northern blot analysis of 25 clinical tumor specimens." (PMID 25472873, 2014). "On the basis of these observations, our findings on Ephexin1’s regulation of 5′-TOP mRNA translation, we hypothesized that mTOR target genes, such as HSP90ab1, eEF1a1 and c-Myc, along with Ephexin1, are involved in lung cancer progression." (PMID 40855114, 2025). "In DMG cells, we found that upregulation of the methyltransferase METTL13 leads to high levels of methylation of the translation regulator EEF1A1 which, consistent with previous reports in Ras-driven pancreatic and lung cancer models, was accompanied by increased rates of protein synthesis." (PMID 39954016, 2025). "The present study found that LNC CRYBG3 can combine with eukaryotic translation elongation factor 1 alpha (eEF1A1), which is not only a translation factor, but also a pleiotropic protein that is highly expressed in human tumors, including breast, ovarian, and lung cancers." (PMID 33809929, 2021). "Moreover, luciferase reporter assays showed that eEF1A1 directly targets the MDM2 promoter region in lung cancer cells and that LNC CRYBG3 has a high affinity for the binding of eEF1A1 to the MDM2 promoter." (PMID 33809929, 2021).